CDKL3 (cyclin dependent kinase like 3)
Diseases named in the same sentence as CDKL3 in open-access papers (continued):
Sharing a sentence is not in itself a finding about the gene and the disease.
tumor (continued). "Additionally, in vivo experiments demonstrated a reduction in tumor volume upon the knockdown of CDKL3." (PMID 38993199, 2024). "In summary, raised CDKL3 expression promoted the tumor immune phenotype to become a ‘cold’ type." (PMID 38562942, 2024). "Furthermore, CDKL3 was found to be involved in various mechanisms linked to the development of HCC, including copy number variation, tumor burden, genomic heterogeneity, cancer stemness, and alternative splicing of CDKL3." (PMID 38993199, 2024). "Overall, CDKL3 may play an important role in anti-tumor immunity by regulating autophagy to promote the formation of immunosuppressive TME, thus playing a critical role in the prognosis of ESCA." (PMID 38562942, 2024). "Furthermore, the ES for the anti-tumor signatures was considerably lower in the CDKL3 high expression group with a higher ES for the TAMsurr_score." (PMID 38562942, 2024). "CDKL3 may play an important role in anti-tumor immunity by regulating autophagy to promote the formation of immunosuppressive TME, thus playing a critical role in the prognosis of ESCA." (PMID 38562942, 2024). "We hypothesized that CDKL3 may alter tumor immunogenicity and immune infiltrating cells within the TME by influencing autophagy induction, thereby affecting immunotherapy patient response and prognosis in ESCA." (PMID 38562942, 2024). "At the end-point of the experiment, tumor size detection using in vivo fluorescence imaging (using fluorescence intensity to characterize tumor size) as well as weighing and photography of tumors further showed that knockdown of CDKL3 expression not only inhibited the in vivo growth of tumors." (PMID 36899018, 2023). "As preclinical and clinical tumor therapies targeting Akt-related pathways spring out robustly in the past decade, we envision that the future CDKL3-specific inhibitors may join the rank either individually or combinatorically." (PMID 32234750, 2020). "This suspicion was further supported by the data shown in OS tissues with the pairing adjacent non-tumor tissues that CDKL3 negatively regulated the bulk Akt, whereas CDKL3 could positively phosphorylate both Akt-T308 and Akt-S473 positions." (PMID 32234750, 2020). "For translational medicine, targeting CDKL3 might be available to provide higher specificity to particular tumor tissues and less toxicity to normal organs." (PMID 32234750, 2020). "Mechanistic detection demonstrated that CDKL3 might promote tumor profession, invasion, metastasis, and prohibit tumor apoptosis partly by ATG5 activation." (PMID 32974198, 2020). "Therefore, CDKL3 played a pivotal role in promoting tumor progression by ATG5 activation, which is a crucial gene involved in autophagy regulation." (PMID 32974198, 2020). "In the CCA tissues, positive CDKL3 was mostly present in the cytoplasm of tumor cells." (PMID 29615928, 2018). "Therefore, we hypothesized that the high expression of CDKL3 in ESCC may attenuate anti-tumor immunity by inhibiting the IFN pathway." (PMID 38562942, 2024). "In addition, CDKL3 expression was also detected by western blot in xenografts to assure whether the change of tumor growth resulted from CDKL3 knockdown." (PMID 36899018, 2023). "Furthermore, CDKL3 may promote tumor profession, invasion, metastasis, and prohibit tumor apoptosis partly by ATG5 activation." (PMID 32974198, 2020). "According to pancancer analysis, the expression of CDKL3 is aberrant in different types of cancer, and it is higher in HCC tumor tissue compared to normal tissue." (PMID 38993199, 2024). "The overexpression of Ki67 showed a positive correlation with that of CDKL3 (P < 0.001 versus CDKL3-low expressed samples), which determines that the shorter survival of patients with CDKL3 overexpression might at least partially be due to subsequent elevated tumor proliferation." (PMID 32234750, 2020).
tumor (continued). "Tumor tissues and adjacent normal tissues from ESCC patients were immunostained for expression of CDKL3 and ATG5, both of which were predominantly localized in the cytoplasm." (PMID 32974198, 2020). "These included genes with homologs involved in tumor suppression (OPCML), cell growth regulation (CDKL3), DNA repair (FANCL), and innate immunity (TMED7-TICAM2)." (PMID 30845962, 2019). "Using Univariate Cox regression analysis, the results confirmed negative correlations between overall survival and gender (p = 0.014), tumor invasion (p = 0.000), lymph-node metastasis (p = 0.000), TNM stage (p = 0.000), and high CDKL3 (p = 0.014) and ATG5 expression (p = 0.007) in ESCC patients." (PMID 32974198, 2020). "This suggested that CDKL3 may reshape the TME by regulating these chemokines and chemokine receptors, leading to the infiltration of immunosuppressive cells, ultimately affecting the response to immunotherapy and the promotion of tumor progression." (PMID 38562942, 2024). "Among all CDKLs, CDKL3 and CDKL4 showed significantly enhanced expression in tumor samples compared with adjacent non-tumor tissues." (PMID 32234750, 2020).
cancer (7 papers, 2018 to 2024). A tumor composed of atypical neoplastic, often pleomorphic cells that invade other tissues. "Though CDKL3 was reported to associate with cancer progression, the mechanism requires further scrutiny with rigorous evidence." (PMID 38963708, 2024). "The design and characterization of a first-in-class CDKL3 inhibitor is necessary, which can potentially provide an alternative therapeutic path in cancer treatment by causing cell cycle arrest." (PMID 38963708, 2024). "CDKL3 loss leads to severe delay of G0-to-G1 and G1-to-S transitions and thus prevents cancer cell cycle progression." (PMID 38963708, 2024). "CDKL3 loss caused severely delayed G0-to-G1 transition and alleviated cancer cell growth." (PMID 38963708, 2024). "CDKL3 loss abrogates cancer cell growth by impeding G0-to-G1 transition." (PMID 38963708, 2024). "It suggests that CDKL3 is likely to be associated with the regulation of malignant tumors." (PMID 36899018, 2023). "Collectively, this work presents an integrated paradigm of cancer cell cycle regulation and suggests CDKL3 targeting as a feasible approach in cancer treatment." (PMID 38963708, 2024). "We analyzed multiple clinical cancer databases to further demonstrate the potential clinical importance of CDKL3." (PMID 38963708, 2024). "We are generating cancer model mice with conditional knockout of Cdkl3 to validate the cell cycle–promoting effect of CDKL3." (PMID 38963708, 2024). "The proposed small-molecule inhibitor against CDKL3 was shown to have great potency in cancer treatment." (PMID 38963708, 2024). "HZ1 showed substantial promise as a therapy for cancer, since it effectively blocks CDKL3-mediated cell cycle progression both in vitro and in vivo." (PMID 38963708, 2024). "Here, we identified that an underappreciated serine/threonine kinase, cyclin-dependent kinase–like 3 (CDKL3), crucially drives rapid cell cycle progression and cell growth in cancers." (PMID 38963708, 2024). "As there are fewer immunotherapy cohorts for ESCA, we investigated the role of CDKL3 in predicting the response to immunotherapy in other cancers." (PMID 38562942, 2024). "Further evidence to support that CDKL3 positively regulated cancer cell growth was provided by the 3D colony formation (AC–AE)." (PMID 38963708, 2024). "In the cancer cells, the accumulation of pRb halted when CDKL3 was ablated and accelerated with ectopic CDKL3." (PMID 38963708, 2024). "CDKL3 contributes to aberrant and oncogenic cell cycle, and its inhibition antagonizes cancer growth in multiple models." (PMID 38963708, 2024). "Combining the findings on the phosphorylation of Rb and CDK4 by CDKL3, we tested the regulatory role of CDKL3 in cancer cell proliferation in vivo." (PMID 38963708, 2024). "We also interrogated the response of the cancer organoids to HZ1 with the genetic modulations of CDKL3, CDK4, or Rb." (PMID 38963708, 2024). "In this work, we identified CDKL3 as a crucial regulator of cell cycle progression in cancer, phosphorylating Rb to initiate the cell cycle from quiescence and preserving CDK4 to maintain G1 phase advancement." (PMID 38963708, 2024). "After rational design and synthesis, we also presented the potent CDKL3 inhibitor HZ1 for cancer treatment." (PMID 38963708, 2024). "Poor response to immunotherapy in patients with high CDKL3 expression was also demonstrated in pan-cancer immunotherapy cohorts." (PMID 38562942, 2024). "Future studies of CDKL3 on different types of tumors and exploring the biological functions of the rest CDKLs in cancer development would be fascinating both in theory and in clinical application." (PMID 32234750, 2020). "To elucidate the molecular mechanisms through which CDKL3 promotes the proliferation of ESCC cancer cells, we analyzed the differential gene expression profiles between KYSE-150-shCtrl and KYSE-150-shCDKL3 cells by Gene Expression Array." (PMID 32974198, 2020). "CDKL3 ablation or overexpression had minimal impact on S phase entry of the cancer cells." (PMID 38963708, 2024).
cancer (continued). "Ablation of CDKL3 results in cell cycle exit and growth retardation in cancers." (PMID 38963708, 2024). "Consequently, CDKL3 can assist the cell cycle progression and cell proliferation in cancer via dual paths — CDK4 stabilization and Rb phosphorylation in parallel." (PMID 38963708, 2024). "The crucial function of CDKL3 in cancers was demonstrated both in vitro and in vivo." (PMID 38963708, 2024). "CRISPR/Cas9 system was used to generate multiple CDKL3-knockout (KO) cancer cell lines." (PMID 38963708, 2024). "Here, we report that CDKL3 directly promotes cell cycle progression in cancer." (PMID 38963708, 2024). "Besides its value for basic biomedical research, this work also presents and proposes an alternative cancer therapeutic approach by targeting of CDKL3-mediated cancer cell cycle progression." (PMID 38963708, 2024). "Moreover, depletion of CDKL3 resulted in evident growth defects in these cancer cell lines, which was in accordance with the cell cycle arrest (AA and AB)." (PMID 38963708, 2024). "On the other hand, because of the accumulating evidence showing the critical role played by MAPKs and CDKs in the development and progression of malignant tumors, more and more studies began to focus on the functions of CDKL3 in the regulation of human cancers." (PMID 36899018, 2023). "The abnormal expression of CDKL3 has been revealed to be related to human cancers." (PMID 32974198, 2020). "Evaluation of the link between CDKL3 expression and phosphorylation of Akt in OS patients may provide a guide for cancer precision medicine and disease prognosis." (PMID 32234750, 2020). "Although a few studies have linked CDKL3 with cancers, the evidence is far lacking in solid support of its role and mechanisms underlying cancer progression." (PMID 32234750, 2020). "Published studies have revealed that CDKL3 is related to human cancers." (PMID 29615928, 2018). "Besides, the role of CDKL3 in ESCC was studied in vitro and in vivo assays, and to exploit whether ATG5 exerts its effects on CDKL3-dependent cancer promotion." (PMID 32974198, 2020). "However, the association between ATG5 and CDKL3 in cancer has not been studied previously." (PMID 32974198, 2020).
adenocarcinoma (1 paper, 2024). A common cancer characterized by the presence of malignant glandular cells. "Based on the public database of ESCA (mainly adenocarcinoma), the results of this study also showed that CDKL3 was highly expressed and associated with shorter survival." (PMID 38562942, 2024).
CDKL3 also shares sentences with these, for which no sentence is quoted: colorectal cancer (2 papers); liver cancer (2); breast carcinoma (1); squamous cell carcinoma (1); T-cell lymphoma (1).